CLSTN2 (calsyntenin 2)
Description:
Postsynaptic adhesion molecule that binds to presynaptic neurexins to mediate synapse formation, and which is involved in learning and memory (By similarity). Promotes synapse development by acting as a cell adhesion molecule at the postsynaptic membrane, which associates with neurexin-alpha at the presynaptic membrane (By similarity).
Synonyms: Alc-gamma; CS2; CSTN2; FLJ39113; CDHR13; alcagamma
Tractability: Antibody: UniProt places it where antibodies can reach, with medium confidence; UniProt predicts a signal peptide or a membrane-spanning region; its Gene Ontology location is reachable by antibodies, with medium confidence. PROTAC: its protein half-life has been measured.
Gene: Protein-coding gene on chromosome 3 (139,935,185 to 140,577,397, forward strand). Ensembl gene ENSG00000158258.
Subcellular location: Postsynaptic cell membrane; Endoplasmic reticulum membrane; Golgi apparatus membrane; Cell projection, dendrite
Subcellular location (Human Protein Atlas): Vesicles; Cytokinetic bridge
Gene Ontology:
Molecular function: cell-cell adhesion mediator activity; calcium ion binding
Biological process: homophilic cell-cell adhesion; positive regulation of synapse assembly; positive regulation of synaptic transmission; associative learning; inhibitory synapse assembly
Cellular component: cell surface; endoplasmic reticulum membrane; Golgi membrane; postsynaptic density membrane; postsynaptic membrane; dendrite; glutamatergic synapse; membrane; postsynaptic density
Genetic constraint (gnomAD): Loss-of-function variants: 46 observed, 101.79 expected, observed/expected ratio (o/e) 0.45, 90% interval 0.36 to 0.58. The upper end of that interval is the gene's LOEUF score, 0.58, which puts it in group 2 of 6, group 1 being the genes least tolerant of losing a copy. Missense variants: 1,139 observed, 1,266.6 expected, observed/expected ratio (o/e) 0.9, 90% interval 0.86 to 0.94. Synonymous variants: 474 observed, 468.89 expected, observed/expected ratio (o/e) 1.01, 90% interval 0.94 to 1.09.
Homologues: Orthologues: chimpanzee CLSTN2 (99% identical), macaque CLSTN2 (98% identical), dog CLSTN2 (95% identical), mouse Clstn2 (95% identical), rabbit CLSTN2 (95% identical), pig CLSTN2 (94% identical), guinea pig CLSTN2 (93% identical), rat Clstn2 (87% identical), tropical clawed frog clstn2 (71% identical), zebrafish clstn2a (65% identical), zebrafish clstn2b (56% identical), Drosophila melanogaster Cals (32% identical), and 1 more. Paralogues in human: CLSTN1 (55% identical), CLSTN3 (47% identical).
Diseases named in the same sentence as CLSTN2 in open-access papers:
CLSTN2 is named in the same sentence as 33 diseases in open-access papers, as found by Europe PMC text mining. Sharing a sentence is not in itself a finding about the gene and the disease. The quoted sentences say what the papers report.
Alzheimer disease (2 papers, 2012 to 2022). A progressive, neurodegenerative disease characterized by loss of function and death of nerve cells in several areas of the brain leading to loss of cognitive function such as memory and language. "CLSTN2 is associated with episodic memory and late-onset Alzheimer’s disease." (PMID 35203526, 2022). "Additionally, NPAS3 has been linked to schizophrenia and bipolar disorder, CLSTN2 has been associated with memory performance and with Alzheimer’s disease, and RBFOX1 (A2BP1) has been very recently discovered as a splicing regulator of neuronal excitation and calcium homeostasis in the brain." (PMID 22888310, 2012).
Obesity (2 papers, 2020 to 2023). Accumulation of substantial excess body fat. "CLSTN2 has an essential role in promoting adipocyte proliferation in visceral adipose tissue and subcutaneous fat and is associated with mammalian obesity." (PMID 37595009, 2023). "CLSTN2 (calmodulin 2) plays an important role in promoting adipocyte proliferation in visceral adipose tissue and subcutaneous fat and is associated with mammalian obesity." (PMID 33391332, 2020).
osteosarcoma (2 papers, 2020 to 2024). A usually aggressive malignant bone-forming mesenchymal neoplasm, predominantly affecting adolescents and young adults. "Future studies could further investigate the expression level of Lnc-CLSTN2-1:1 in clinical samples and explore its clinical application value as a potential diagnostic marker or therapeutic target for osteosarcoma." (PMID 38356713, 2024). "By activating the PI3K/AKT signaling pathway, Lnc-CLSTN2-1:1 promoted the proliferation and metastasis of osteosarcoma cells and led to excessive accumulation of ROS." (PMID 38356713, 2024). "This research aimed to assess the usefulness of Lnc-CLSTN2-1:1 in osteosarcoma and analyze its probable pathways." (PMID 38356713, 2024). "Next, we detected Lnc-CLSTN2-1:1 in the osteosarcoma HOS cell line and fibroblast cells using qRT-PCR." (PMID 38356713, 2024). "After analyzing the biological effects of Lnc-CLSTN2-1:1 using in vitro assays, we present in vitro evidence supporting the oncogenic impact of Lnc-CLSTN2-1:1 in osteosarcoma." (PMID 38356713, 2024). "Clinical transformation: Although this study has preliminarily explored the role of Lnc-CLSTN2-1:1 in osteosarcoma, its clinical application prospects are still unclear." (PMID 38356713, 2024). "Our study found that the expression level of long non-coding RNA (lncRNA) Lnc-CLSTN2-1:1 is elevated in osteosarcoma and promotes the progression of osteosarcoma by interfering with intracellular REDOX balance." (PMID 38356713, 2024). "Using the knockdown test CCK8, clone creation, EdU assay, and transwell assay, we found that Lnc-CLSTN2-1:1 significantly contributed to the progression of osteosarcoma in terms of value-added, invasion, and migration." (PMID 38356713, 2024). "The proliferation, invasion, and migration of osteosarcoma cells were significantly inhibited by knockdown of the expression of Lnc-CLSTN2-1:1, and the cell cycle-related signaling pathway PI3K/AKT/GSK-3β/cycinD1 was also inhibited." (PMID 38356713, 2024). "Materials and procedures: We selected differentially overexpressed Lnc-CLSTN2-1:1 from our laboratory's existing RNA sequence analysis data (fibroblast osteoblast (hFOB 1.19) and three osteosarcoma cell lines (HOS, MG63, and U2OS) as the research object." (PMID 38356713, 2024). "In addition, CLSTN2 was demonstrated to be involved in both the tumorigenesis and pulmonary metastasis of osteosarcoma." (PMID 33194689, 2020). "The biological function and mechanism of action of Lnc-CLSTN2-1:1 in osteosarcoma have not been described." (PMID 38356713, 2024). "To determine the impact of Lnc-CLSTN2-1:1 on the cell cycle via the PI3K/AKT pathway, which contributes to the malignant biological behavior of osteosarcoma, we pretreated cells with igf-1 (PI3K /Akt agonist) and then measured the protein levels of P-AKT and cyclinD1." (PMID 38356713, 2024).
Anxiety (1 paper, 2021). Intense feelings of nervousness, tension, or panic often arise in response to interpersonal stresses. "For example, Ntrk3, Tnr, Cacna1h, Clstn2, and Rapgef2 were found to be involved in pathological processes of anxiety." (PMID 33431988, 2021).
Arthritis (1 paper, 2018). Inflammation of a joint. "Nevertheless, some of these genes participate in nervous system development (CLSTN2, TUBB2B), inflammation including arthritis (AOC3) and stress-induced responses (C10orf10), making them promising molecular candidates in OA-driven pain." (PMID 29973527, 2018).
Cirrhosis (1 paper, 2022). A chronic disorder of the liver in which liver tissue becomes scarred and is partially replaced by regenerative nodules and fibrotic tissue resulting in loss of liver function. "In Iceland (SomaScan), the most significant difference between NAFL and cirrhosis was, first, for calsyntenin 2 (CSTN2, P = 3.6 × 10−17, effect = 0.92 s.d)." (PMID 36280732, 2022).
Dyskinesia (1 paper, 2022). A movement disorder which consists of effects including diminished voluntary movements and the presence of involuntary movements. "In contrast, serotoninergic neurons, the potential source of graft-induced dyskinesia, and GABAergic neurons were largely absent from the CLSTN2- and PTPRO-sorted grafts." (PMID 35700056, 2022).
Esophageal Carcinoma (1 paper, 2020). A primary or metastatic malignant neoplasm involving the esophagus. "Higher gene expression of CLSTN2 is associated with poor overall survival in the TCGA-Esophageal Carcinoma dataset (p-value = 0.05)." (PMID 32974170, 2020).
liver fibrosis (1 paper, 2021). "Furthermore, the expression of Fst is associated with liver fibrosis, while the downregulation of Clstn2 was observed in progressive RA." (PMID 34208308, 2021).
tumor (4 papers, 2017 to 2024). "After 28 days after inoculation, Lnc-CLSTN2-1:1 knockdown dramatically decreased tumor development relative to that in the control group." (PMID 38356713, 2024). "The results indicated that AIFM3, HSH2D, and PTPN6 were significantly up-regulated, while DCHS1, PTGIS, FLRT2, PCSK5, and CLSTN2 were significantly down-regulated in tumor samples compared with normal samples." (PMID 34512722, 2021). "To determine whether Lnc-CLSTN2-1:1 has the same effect in vivo, we assessed the effect of Lnc-CLSTN2-1:1 on tumor development using tumor xenografts in nude mice." (PMID 38356713, 2024). "Lnc-CLSTN2-1:1 knockdown decreased tumor development in vivo, according to the data obtained." (PMID 38356713, 2024). "Moreover, the expression levels of LEP, DLX2, CLSTN2, and REG3A were significantly higher in tumor tissues than normal tissues." (PMID 33194689, 2020).
cancer (2 papers, 2024 to 2025). A tumor composed of atypical neoplastic, often pleomorphic cells that invade other tissues. "Redox alterations can change the fate of cancer cells, and whether Lnc-CLSTN2-1:1, a regulatory gene with no self-encoding ability, affects the redox balance within cancer cells to promote cancer development." (PMID 38356713, 2024).
metabolic disorders (1 paper, 2025). "The expression of the CLSTN2 gene is associated with glucose and insulin metabolism, contributing to their regulation and the onset of metabolic disorders." (PMID 40509051, 2025).
psychiatric disorder (1 paper, 2018). A disorder characterized by behavioral and/or psychological abnormalities, often accompanied by physical symptoms. "The present study detects three psychiatric disorder‐relevant genes (CLSTN2, FAT1, and SLC18A1) that have been under positive selection during the human evolution." (PMID 30283697, 2018).
CLSTN2 also shares sentences with these, for which no sentence is quoted: Astigmatism (2 papers); colorectal cancer (2); atypical teratoid rhabdoid tumor (1); B cell lymphoma (1); bipolar disorder (1); bladder cancer (1); breast carcinoma (1); Cholecystitis (1); dementia (1); depression (1); dyslexia (1); ependymoma (1); glioblastoma (1); hematological malignancies (1); hepatocellular carcinoma (1); Onset (1); restless legs syndrome (1); schizophrenia (1); spinocerebellar ataxia (1); xeroderma pigmentosum (1).